INS (insulin)
Diseases named in the same sentence as INS in open-access papers (continued):
Sharing a sentence is not in itself a finding about the gene and the disease.
type 1 diabetes (continued). "Type 1 diabetes (T1D) is a chronic autoimmune condition resulting from immune‐mediated destruction of pancreatic islet beta cells, and a lifelong dependence on exogenous insulin therapy." (PMID 39623620, 2025). "For instance, volagidemab (REMD-477), a monoclonal antibody targeting GCGR, has been shown to reduce insulin requirements and lower mean daily glucose by approximately 27 mg/dL over 24 hours in individuals with type 1 diabetes, without increasing the risk of hypoglycemia." (PMID 40822953, 2025). "Type 1 diabetes mellitus (T1DM), which typically manifests during childhood, adolescence, or early adulthood, has an autoimmune origin that prevents the pancreas from producing insulin." (PMID 40917291, 2025). "Type 1 diabetes (T1D) is an organ-specific autoimmune disease that is brought on by the immune system targeting and destroying the pancreatic beta cells that produce insulin." (PMID 40299229, 2025). "Encompassing 51 children with T1D and 69 healthy controls, revealed that children with type 1 diabetes had a mean HbA1c level of 9.4 ± 0.2, and a mean insulin dose of 0.94 units/kg/day." (PMID 38879626, 2025). "Several factors may underlie this discrepancy: First, predominant use of type 1 diabetes models (STZ-induced mice) in preclinical studies inadequately replicates the complex metabolic milieu of human type 2 DKD, particularly regarding insulin resistance and dyslipidemia interactions." (PMID 41485909, 2025). "Type 1 diabetes mellitus (T1DM) is a multifactorial autoimmune disease characterised by a gradual loss of insulin-secreting pancreatic β cells as a function of non-mutually exclusive events, including destruction by T-cell mediated responses and de-differentiation." (PMID 40004501, 2025). "Type 1 diabetes (T1D) is a complex, chronic autoimmune disease that typically manifests in childhood and adolescence, requiring lifelong insulin therapy and comprehensive care." (PMID 40887640, 2025). "Type 1 diabetes mellitus (T1D) is a chronic organ-specific autoimmune disease, characterized by the immune-mediated destruction of insulin-producing pancreatic β-cells." (PMID 41463376, 2025). "Islet transplantation offers a promising treatment for type 1 diabetes (T1D), by aiming to restore insulin production and improve glycemic control." (PMID 40344470, 2025). "Type 1 diabetes (T1D) is characterised by the autoimmune destruction of pancreatic insulin-producing beta cells, leading to a lifelong dependency on exogenous insulin administration for survival." (PMID 40718205, 2025). "The majority of international guidelines recommend automated insulin delivery (AID) systems as the standard of care for people living with type 1 diabetes (T1D), both for adult and pediatric populations." (PMID 41488135, 2025). "A neural induction medium developed with physiological insulin and glucose levels allows modeling of gestational and type 1 diabetes (T1D), aiding in the study of early brain development and neurocognitive effects." (PMID 40801620, 2025). "Maintaining endogenous insulin secretion in type 1 diabetes (T1D) long after its onset, and thus the need for early diagnosis and searching for factors preserving the secretory function of β-cells, has become an important goal of current research." (PMID 40607224, 2025). "The addition of SGLT2i to insulin therapy in type 1 diabetes (T1D) is an emerging treatment strategy." (PMID 40347422, 2025). "The ketogenic diet has attracted significant interest for its potential benefits in improving blood sugar regulation and decreasing the need for insulin in people with type 1 diabetes (T1D)." (PMID 41149081, 2025). "However, the diagnosis of ‘other eating disorder’ is not necessarily less severe than anorexia nervosa or bulimia nervosa among those with type 1 diabetes; it could also reflect atypical features of eating disorders, such as insulin omission." (PMID 39755842, 2025).
type 1 diabetes (continued). "Type 1 diabetes (T1D) necessitates lifelong insulin therapy due to the autoimmune destruction of insulin-producing pancreatic beta cells." (PMID 40022528, 2025). "Multiplexed sensing is particularly beneficial for managing Type 1 Diabetes (T1D), offering crucial data for personalizing insulin dosages and understanding relationships between biomarkers under various physiological conditions." (PMID 40742490, 2025). "Type 1 diabetes (T1D) is an autoimmune condition characterized by the destruction of insulin-producing beta cells in the pancreas." (PMID 40359439, 2025). "Therefore, in cases where SGLT2 inhibitors are used in conditions with decreased insulin secretion, including type 1 diabetes, it is necessary to pay attention not only to blood sugar but also to changes in body composition, including muscle mass and bone mineral density." (PMID 41373820, 2025). "Type 1 diabetes (T1D) is a chronic autoimmune disease characterized by the destruction of insulin-producing beta cells in pancreatic islets." (PMID 40585213, 2025). "Type 1 diabetes mellitus (T1DM) develops due to autoimmunity against the insulin-producing beta cells of the pancreas." (PMID 41275187, 2025). "Type 1 diabetes (T1D) is a chronic autoimmune disease that inhibits the production of insulin, preventing the intrinsic regulation of blood glucose (BG)." (PMID 41264796, 2025). "Furthermore, research indicates that the fermentation products of Leuconostoc mesenteroides, including butyrate and other short‐chain fatty acids, can regulate insulin and blood glucose levels in Type 1 diabetes mice, as well as reduce abdominal fat accumulation induced by a high‐fat diet." (PMID 39968210, 2025). "Type 1 diabetes (T1D) is an autoimmune disease characterized by the immune-mediated destruction of insulin-producing β-cells, leading to chronic hyperglycemia." (PMID 41141358, 2025). "Type 1 diabetes (T1D) results from autoimmune destruction of insulin-secreting β cells by islet-infiltrating CD4 and CD8 T cells." (PMID 40684438, 2025). "Type 1 diabetes mellitus (T1D) occurs due to the inability of pancreatic B-cells to produce sufficient insulin." (PMID 40775339, 2025). "Among the organs explored for 3D bioprinting, the pancreas, specifically its endocrine compartment, presents a uniquely defined clinical target: the restoration of insulin secretion in patients with type 1 diabetes mellitus (T1DM)." (PMID 41149702, 2025). "As of today, exogenous insulin supplementation remains the main approach allowing an acceptable control of blood glucose levels in type 1 diabetes (T1D) patients." (PMID 40339569, 2025). "Although SGLT2is are typically used in patients with type 2 diabetes and are not approved for those with type 1 diabetes in many countries, they have been used off-label as adjunctive therapy to insulin in some cases, raising concerns regarding an increased risk of SGLT2i-associated EDKA." (PMID 40951123, 2025). "Insulin therapy in type 1 diabetes may also influence nutritional intervention responses." (PMID 40641818, 2025). "Type 1 diabetes (T1D) is an autoimmune disorder characterized by the destruction of insulin-producing pancreatic beta-cells, leading to lifelong insulin dependence." (PMID 39860426, 2025). "Autoimmune diabetes, also known as type 1 diabetes mellitus (T1DM), is a chronic condition characterized by immune-mediated destruction of insulin-producing beta cells in the pancreas." (PMID 39859557, 2025). "Hybrid closed‐loop (HCL) insulin delivery systems represent a major advance in type 1 diabetes (T1D) management, automating insulin adjustments using real‐time glucose data." (PMID 40631447, 2025). "Whilst insulin therapy remains the mainstay treatment for type 1 diabetes mellitus (T1DM), the European Society of Cardiology recommends SGLT2is as a first‐line drug therapy for ASCVD patients diagnosed with T2DM." (PMID 40173289, 2025).
type 1 diabetes (continued). "Any presentation of new-onset diabetes mellitus in a youth requires consideration of both types, as rarely patients presenting with excessive adiposity may also have autoantibodies; the latter heralds type 1 diabetes (T1D) and the requirement of management with insulin." (PMID 39552817, 2024). "Low adherence to the number of insulin injections and glycemic variability are among the challenges of insulin therapy in type 1 diabetes (T1D)." (PMID 38982528, 2024). "The development of engineered cells that can secrete endogenous insulin offers a promising new therapeutic strategy for type 1 diabetes (T1D)." (PMID 39279997, 2024). "In the etiology of type 1 diabetes mellitus (T1D), β cells are selectively targeted by autoimmunity, resulting in islet inflammation and reduced insulin production and secretion." (PMID 39666939, 2024). "Furthermore, in type 1 diabetes, the lack of insulin was associated with a higher risk of osteopenia and osteoporosis at a young age." (PMID 38541119, 2024). "Decreased β-cell HIF1α could contribute to type 1 diabetes pathogenesis by increasing sensitivity to apoptosis, increasing β-cell stress (as HIF1α mediates a protective response to stress), and by increasing the load of improperly folded insulin." (PMID 39769216, 2024). "Insulin was discovered in 1921-22 with the extraction and purification of a pancreatic substance that could effectively lower blood glucose levels in patients with Type 1 diabetes." (PMID 38131197, 2024). "Lack of insulin access is the leading cause of death in children with type 1 diabetes in sub-Saharan Africa, and some patients may live just 1 year after diagnosis due to intermittent insulin availability." (PMID 39464844, 2024). "Type 1 diabetes (T1D) is a chronic autoimmune disease in which the immune system attacks the insulin-producing beta cells of the pancreas, thereby significantly reducing the body’s insulin secretion, leading to increasing blood glucose levels and risk for cardiovascular disease (CVD)." (PMID 39280005, 2024). "More than 8.4 million people worldwide are currently impacted by type 1 diabetes mellitus (T1D), resultant from autoimmune destruction of the insulin-producing pancreatic beta cells." (PMID 38776307, 2024). "However, other studies have shown higher rates of DKA with insulin pumps in type 1 diabetes." (PMID 38907161, 2024). "TeKnO T1D demonstrated its effectiveness in enhancing endocrinology fellows’ knowledge and confidence in utilizing insulin pumps and CGM for managing pediatric type 1 diabetes." (PMID 39463462, 2024). "Therefore, smart insulin pens may have the potential to improve adherence and achieve glycaemic targets in type 1 diabetic pregnancies, which are important for maternal and foetal outcomes." (PMID 39791645, 2024). "As screening programmes identify more people with early-stage type 1 diabetes, more people are being assessed as meeting classic diagnostic criteria for stage 3 type 1 diabetes, but who might not yet require insulin therapy." (PMID 38910151, 2024). "Type 1 diabetes (T1D) is a chronic autoimmune disease characterized by the destruction of pancreatic β-cells, resulting in impaired insulin secretion and high levels of blood glucose." (PMID 38166933, 2024). "Multiple lines of evidence show that type 1 diabetes (T1D) develops due to CD8+ T cell–mediated destruction of insulin-producing pancreatic β cells." (PMID 39286976, 2024). "Type 1 diabetes (T1D) is a metabolic disease resulting from progressive autoimmune destruction of insulin-producing pancreatic beta cells." (PMID 38534794, 2024). "Differentiation of adipocytes is not as much directly linked to type 1 diabetes, nonetheless, metabolic dysregulation and resistance of insulin may still happen in persons with this illness." (PMID 38371502, 2024). "The aim of this study was to assess the efficacy and safety of hybrid closed-loop (HCL) systems for insulin delivery in children and adolescents with type 1 diabetes (T1D)." (PMID 38602747, 2024).
type 1 diabetes (continued). "However, the prevalence of eating disorders may still be high as intense insulin treatment is based on carbohydrate counting, in practice “diet”, and food habits are still an important part of type 1 diabetes treatment." (PMID 38198020, 2024). "Type 1 diabetes, is a chronic lifelong auto-immune condition characterised by the bodily destruction of one’s pancreatic insulin producing beta cells, requiring an intense management regime of multiple daily injections (MDIs) or pump therapy to provide artificial insulin." (PMID 38158848, 2024). "The main cause of type 1 diabetes (T1D) is islet infiltrated by antigen-specific autoreactive T cells and consequent autoimmune-mediated islet β cell destruction, eventually lead to a complete lack of insulin." (PMID 38343632, 2024). "Islet transplantation, a promising treatment for type 1 diabetes (T1D), aims to restore insulin production and achieve better glucose control." (PMID 39267737, 2024). "Type 1 diabetes (T1D) is characterized by autoimmune destruction of insulin-producing β-cells within pancreatic islets." (PMID 39678192, 2024). "Insulin replacement is the established therapy of type 1 diabetes mellitus (T1DM) since hundred years." (PMID 39420138, 2024). "We will focus on type 1 diabetes (T1D), which is an autoimmune disease characterized by irreversible destruction of insulin-producing β cells in the Langerhans islets of the pancreas." (PMID 38097717, 2024). "In type 1 diabetes (T1D), the pancreas is depleted of β cells and, hence, of cell-regulated provision of insulin according to metabolic needs." (PMID 38012450, 2024). "Recently, a hybrid closed-loop insulin delivery system could be available in type 1 diabetes." (PMID 38541176, 2024). "Type 1 Diabetes Mellitus (T1DM) is the resulting condition of the autoimmune destruction of beta-pancreatic cells, which are responsible for insulin production." (PMID 38891851, 2024). "In type 1 diabetes (T1D), the autoimmune process leads to the selective destruction of insulin-producing beta cells within pancreatic islets." (PMID 38975343, 2024). "Poorly controlled adolescents living with type 1 diabetes (T1D) and pump failure of insulin delivery leading to diabetic ketoacidosis (DKA) are still challenging in the western world." (PMID 38762619, 2024). "Type 1 Diabetes Mellitus (T1DM) is a chronic disease that presents with high blood sugar resulting from insufficient secretion of insulin due to the destruction of beta cells in the pancreas." (PMID 38864877, 2024). "Since its introduction in 1921, insulin has changed the management and prognosis of patients with type 1 diabetes (T1D)." (PMID 39906033, 2024). "Exogenous insulin may blunt the metabolic response to exercise in type 1 diabetes." (PMID 38662134, 2024). "The pathogenesis of type 1 diabetes (T1D) involves a complex interplay between multiple cell types within the pancreatic islet, including innate immune cells (macrophages, dendritic cells), insulin-producing cells (β cells), and adaptive immune cells (T cells, B cells)." (PMID 39531315, 2024). "Type 1 diabetes (T1D) is characterized by the autoimmune destruction of insulin-producing β cells and involves an interplay between β cells and cells of the innate and adaptive immune systems." (PMID 39531315, 2024). "Type 1 diabetes mellitus (T1D) is an autoimmune disease against pancreatic beta-cells, reducing insulin production." (PMID 38610687, 2024). "Type 1 diabetes (T1D) results from the immune-mediated destruction of insulin-producing pancreatic beta cells." (PMID 38582818, 2024). "Reaching and maintaining optimal glycemic control while avoiding both hypo- and hyperglycemia remains a daily challenge for people living with type 1 diabetes (T1D), despite advances in insulin therapy and glucose monitoring options." (PMID 38701088, 2024).
type 1 diabetes (continued). "Consequently, different mechanisms may contribute to the development of immunologic destruction of pancreatic beta cells, presenting potential targets for delaying or enhancing insulin production in type 1 diabetes." (PMID 39749265, 2024). "In fact, the DCCT demonstrated that intensive insulin therapy is more effective than conventional treatment in patients with type 1 diabetes (T1D)." (PMID 38542165, 2024). "Type 1 diabetes mellitus (T1D) is a multi-factorial disease resulting from autoimmune destruction of pancreatic β cells, limiting the body ́s ability to produce insulin." (PMID 39243072, 2024). "Type 1 diabetes (T1D) is characterized by self-reactive T cells that damage insulin-secreting beta cells in the pancreatic islet of Langerhans." (PMID 39669576, 2024). "Type 1 diabetes mellitus (T1DM) is a chronic autoimmune disorder characterized by the destruction of insulin-producing beta cells in the pancreas." (PMID 39211721, 2024). "In contrast, glycaemic optimisation using sensor-augmented insulin pump therapy and continuous glucose monitoring (CGM) systems reduced glycaemic variability and improved time in range, which was associated with a reduction in albuminuria in people with type 1 diabetes and DKD." (PMID 38902524, 2024). "In this cohort study of 2738 hospitalized children with insulin-dependent diabetes, hyperglycemic days were significantly decreased in those using a hospital-managed insulin pump (15.7%) and a caregiver-managed home insulin pump (27.0%) compared with those receiving insulin injections (45.2%)." (PMID 38324312, 2024). "The fact that we could not see the ‘morning’ effect (a favourable effect of earlier food intake) in our population could be due to the fact that endogenous insulin, which has a circadian rhythm, may play a less important role in individuals with type 1 diabetes." (PMID 38967668, 2024). "Despite therapeutic and technological advances, self-managing insulin therapy remains challenging for women with type 1 diabetes (T1D)." (PMID 35254146, 2023). "In this study we show that IFNα and IFNγ differentially regulate the proteasomal composition of beta cells and demonstrate that INS-DRiP peptide recognition may be involved in later phases of type 1 diabetes pathogenesis as an amplificatory phenomenon of beta cell destruction." (PMID 37581620, 2023). "Type 1 diabetes (T1D) is a chronic autoimmune disease with an insufficient insulin release due to a destruction of pancreatic β-cells, resulting in hyperglycemia." (PMID 37297566, 2023). "The classical therapy of type 1 diabetes mellitus (T1DM) consists of a predefined daily schedule of subcutaneous injections of insulin." (PMID 37655113, 2023). "Simultaneous pancreas–kidney transplantation (SPKT) can improve long-term patient survival and restore endogenous insulin secretion in recipients with type 1 diabetes (T1D)." (PMID 37174997, 2023). "High apolipoprotein A1 in type 1 diabetes may be due to exogenous insulin." (PMID 38084202, 2023). "However, few studies have shown that T1DM can promote the increase of left ventricular mass, which may be related to the younger age and insulin therapy in patients with type 1 diabetes." (PMID 38250736, 2023). "Type 1 diabetes (T1D) is a chronic autoimmune disease that attacks the insulin-producing b cells of the pancreatic islets." (PMID 37685398, 2023). "Type 1 diabetes (T1D) patients’ lifestyle and prognosis has remarkably changed over the years, especially after the introduction of insulin pumps, in particular advanced hybrid closed loop systems (AHCL)." (PMID 36983941, 2023). "Indeed, female hormonal spikes in puberty influence insulin sensitivity in type 1 diabetes." (PMID 36700969, 2023).